PIK3CA (phosphatidylinositol-4,5-bisphosphate 3-kinase catalytic subunit alpha)
Diseases named in the same sentence as PIK3CA in open-access papers (continued):
Sharing a sentence is not in itself a finding about the gene and the disease.
cancer (continued). "PIK3CA and AKT1/2 are two of the main members of the PI3K/AKT/mTOR signalling pathway, which is often activated in a range of cancers and contributes to their development." (PMID 37352361, 2023). "Several studies have reported that PIK3CA and PTEN are the two most frequently altered genes of the PI3K/Akt/mTOR pathway in human cancers such as colorectal and breast cancer." (PMID 37900167, 2023). "Among these potential druggable alterations, EGFR, KRAS, and PIK3CA gene alterations were the most common, while CDK pathway (CDK4/6, CDKN2A/2B), FGFR1/2/3, BRAF, RET was uncommon across pan-cancer." (PMID 36910668, 2023). "Similarly, people with rare mosaic genetic activation of PIK3CA are not predisposed to cancer in adulthood, although it has to be noted that PIK3CA mutations in these patients are present in different tissues than the tissue types with somatic PIK3CA mutations in sporadic cancer." (PMID 37225977, 2023). "Activating mutations in key factors of the PI3K/AKT/mTOR pathway, such as PIK3CA, AKT, or MAP3K3, lead to the activation of PI3K signaling and uncontrolled cell proliferation in many human cancers." (PMID 37109059, 2023). "It has been observed that a number of NRGs, including DNASE1, HMGB1 and PIK3CA, undergo gains in SCNV across a variety of cancer types, which was consistent with previous studies." (PMID 37408763, 2023). "In all subtypes, four genes—PIK3CA, RHPN2, CRIPAK, and CDH1, were identified as cancer drivers (ZF10)." (PMID 37454130, 2023). "PIK3CA, a component of the PI3K pathway, has been found to play an important role in numerous types of cancers and is considered an oncogene." (PMID 36043445, 2023). "Although our data suggest that the nuclear p85β-USP7-EZH1/2 pathway is activated in cancer cells with a PIK3CA helical domain mutation, we cannot rule out the possibility that this pathway could also be triggered by certain physiological stimuli in normal cells as well." (PMID 35418124, 2022). "We found that USP13 gene amplification is common in cancers, and USP13 significantly co-expressed with PIK3CA in PCa tissues." (PMID 36564767, 2022). "In the PPI network, the core targets, including AKT1, CREB1, CDC42, SIRT1, PIK3CA, and MMP9, are key cancer‐related genes, which further indicate the important role of miR‐204‐5p in human cancers." (PMID 35908280, 2022). "By contrast, in vitro studies have identified alterations in MYC, mTOR, and PIK3CA, but notably rarely KRAS alterations, as potential drivers of resistance in MET-addicted cancer cells with MET-amp." (PMID 35326531, 2022). "Some genes played well-prognostic factors in cancers, for example, MAFK in KICH, MAPK3 in PCPG and MESC, NRF2 in UVM, and PIK3CA in KIRC." (PMID 35242279, 2022).
cancer (continued). "PPI analysis showed potential interactions between three cancer driver genes (AKT1, KRAS, and PIK3CA) and candidate genes (CCNE2, RAD51, and NEIL3)." (PMID 36233194, 2022). "Finally, ranking cancer driver mutations by their correlation with glutamine reveals that KRAS and ERBB4 have the strongest negative correlation (indicating that mutation is associated with a reduction of glutamine), and PRCC, JUN and PIK3CA mutations rank highly with an accumulation of glutamine." (PMID 36321551, 2022). "Although several studies determined the direct or indirect network between PIK3CA, KDR, GAB1, VEGFA, PLCG, and CRKL and hsa-miR-429 in various cancers, the functional regulation of these genes in Bag-1 deficiency conditions is still needed to elucidate." (PMID 37533517, 2022). "According to the prediction and molecular docking results presented in this study, erianin shows high potential to interact with molecules like PIK3CA, RET, KIT, ABL1, and FLT3 in cancers, all of which were found to play important roles in cancer progression." (PMID 35372513, 2022). "Results of further gene-level analysis revealed that the SCNAs of known cancer-related genes, such as PTK6 (44.6%), ERBB3 (13.4%), PIK3CA (11.8%), and UBR5 (11.8%), were relatively frequent (eFigure 4 in Supplement 1)." (PMID 36484990, 2022). "Western blot analysis also showed that knockdown of POLE2 inhibited the expression levels of Cancer-related pathway proteins including p-Akt, CCND1, MAPK9, and PIK3CA." (PMID 33644060, 2021). "Genes such as EGFR, PIK3CA, DROSHA, MDM4, and APC were located inside recurrently aberrant regions, while other known cancer-genes such as NF1, MET and mTOR were identified as cis-genes and located outside the most recurrently altered regions." (PMID 34625038, 2021). "It is worth highlighting the presence of predictive biomarkers for drugs that are currently in use for treating different cancers, such as PARP, ERBB2, EGFR, PIK3CA, mTOR, and Hedgehog signaling inhibitors." (PMID 34575676, 2021). "PIK3CA and PTEN serve as central regulators of the PI3K/AKT/mTOR pathway and are known as bona fide HNSCC cancer genes." (PMID 35047999, 2021). "Some cancer-related factors including Akt, p-Akt, CCND1, CDK6, and PIK3CA were detected by the western blot." (PMID 33996561, 2021). "We used western blotting to investigate the expression of several factors that are known to play significant roles in human cancers, including CDK6, Cyclin D1, PIK3CA, P-AKT, and P-mTOR." (PMID 34966665, 2021). "Western blot analysis also showed that knockdown of POLE2 inhibited the expression levels of cancer-related pathway proteins including p-Akt, CCND1, and PIK3CA, while the expression of MAPK9 was promoted." (PMID 33644060, 2021). "Most known cancer genes have been found through primary cytogenetic analyses, although sequencing of cancer genomes has revealed new cancer genes including BRAF, EGFR, ERBB2, PIK3CA, PPP2R1A, and JAK2." (PMID 34298667, 2021). "A number of studies have shown that the PI3K/Akt pathway in human cancers, especially the expression of the two important genes PIK3CA and PTEN, usually significantly changes in human cancers, which have been found in more than 70% of tumor types." (PMID 33859949, 2021). "A recent comprehensive analysis on oral squamous cell carcinoma (OSCC) identified secondary genetic alterations, including PIK3CA, ZNF750 and EP300 as candidate cancer driver genes." (PMID 34152564, 2021).
cancer (continued). "We observed lower mutation frequencies in PIK3CA in our IBC cohort than previous ones, which may be due to sampling bias arising from the small sample size, as PIK3CA was more frequently mutated in hormone receptor-positive (HR+) cancers, and our study had a lower fraction of HR+ cases." (PMID 33902690, 2021). "Our results provide support for the development of clinical trials evaluating combined p110α (BYL719) and AR inhibition in patients with mCRPC harboring PIK3CA-mutant, PTEN wild-type cancers." (PMID 34417459, 2021). "The hub genes (PIK3CA, STRN, C9orf102, REST, and NHLRC2) obtained from LinkedOmics were submitted to GSCALite for cancer pathway activity and drug sensitivity analysis." (PMID 34367282, 2021). "In line with our previous report, this study demonstrates a key role for PIK3CA in driving EMT and CSC phenotypes during cancer progression." (PMID 31600013, 2020). "Genomic profiling of ESCC tumors found 98% patients having amplification in one or more cancer‐relevant genes, as well as the co‐amplification of genes at adjacent chromosome locations, such as CCND1/FGF19 and TERC/SOX2/PIK3CA." (PMID 31851786, 2020). "The crucial molecules PIK3CA, AKT1, PTEN, and mTOR in the PI3K/Akt and mTOR pathways were all frequently dysregulated in different types of cancer." (PMID 32863943, 2020). "A number of clinical trials are also underway to evaluate the role of aspirin as an adjunct therapy for colorectal, breast and other cancers (ASCOLT, ASPIRIN, US Aspirin Breast Cancer (ABC) trial, PIK3CA based trials and the Add-Aspirin trial)." (PMID 32153653, 2020). "Emerging evidence suggests that PIK3CA has a vital role in regulating EMT and CSC properties in a variety of cancers." (PMID 31600013, 2020). "In particular, PIK3CA H1047L, ATM R2443Q, and ERBB3 V104M are well-documented substitutions that are found in both cancer and hereditary disease." (PMID 33009502, 2020). "The results of interactive network analysis provide new perspectives on the role of hub genes, along with RYR2, ERBB2, PIK3CA, and HELZ2, with respect to the development of GC by querying multidimensional cancer genomics data in cBioPortal." (PMID 32801999, 2020). "Similarly, continued studies of PSCs and their derivatives may also help explain the apparent lineage skewing and relative lack of increased cancer risk in overgrowth patients with the embryonic acquisition of otherwise highly oncogenic PIK3CA mutations." (PMID 32010943, 2020). "In comparison, the well-known oncogene PIK3CA was found critical in 29 cell lines, further strengthening the importance of studying ADSL in cancer." (PMID 31729379, 2019). "The significant increase in transcriptional activity elicited by lactate in both PIK3CA and AKT1 implicates lactate as a signaling oncometabolite of the key PIK3/AKT/mTOR pathway involved in the development of many cancers." (PMID 32010625, 2019). "This included genes like, PIK3R2, PIK3CA, BIRC2 and ZBTB14 with implications in cancer that were over-expressed with FC above ≥10 in OS-DW in comparison to OS-R; while, expression of WNT5A, PIK3CB, ACVR1, MAPK13 and GBX2 were significantly reduced." (PMID 31690262, 2019).
cancer (continued). "We, therefore, analyzed LPAR4, PIK3CA and PTEN genes in TCGA data of pan-cancer cell lines and tumors." (PMID 31289610, 2019). "As expected, known cancer proteins BRAF, PIK3CA, KRas, Akt1, IDH1, and NRas showed the highest hotspot mutation scores in the TCGA dataset." (PMID 31345222, 2019). "Known cancer drivers NOTCH1, PPP6C, RAC1, EIF4G1, PIK3CA showed significant increase in frequency of SCNA in transition from PPOLs to HNSCC that correlated with their expression." (PMID 31427592, 2019). "EGFR, IGF1R, LAMA2, MYLK, PIK3CA, PIK3R1, and MYLK are members of the focal adhesion pathway, whose dynamics are highly altered in cancer cells." (PMID 31024613, 2019). "The underlying mechanism can be related to the downregulation of PIK3CA and GRB2, which are crucial for growth, proliferation, survival, and migration of cancer cells." (PMID 31719636, 2019). "For example, the top 15 SGA-FIs (ranked according to the FDR p values of overlapping DEG sets) that share DEGs with PIK3CA include PTEN, CDH1, ERBB2, and GATA3, which are known cancer drivers, and their connections agree with existing knowledge." (PMID 31276486, 2019). "SOX2 can enhance translation of oncogenic proteins driven by key cancer transcription factors, including NFE2L2, while signaling from PIK3CA can maintain NFE2L2 protein levels." (PMID 31395880, 2019). "To determine the consequences of genetic PIK3CA activation in a developmental context of relevance to both PROS and cancer, we engineered isogenic human induced pluripotent stem cells (iPSCs) with heterozygous or homozygous knockin of PIK3CAH1047R." (PMID 30948643, 2019). "Our analyses resulted in the identification of an ER-positive HRAS-/PIK3CA-/AKT1-wild type AME harboring an HMGA2-WIF1 fusion gene, which has been described in PAs and carcinomas ex-PA of the salivary gland." (PMID 30675516, 2019). "Many of the fusion genes described here have been shown in other cancers to affect the MEK/ERK, PIK3CA, and NF-κB pathways, and are therefore likely to be functional in MM too." (PMID 29654269, 2018). "It is possible that the increased frequency of PIK3CA copy number gain seen in primary and advanced primary PSCC is a by-product of increasing genomic instability with cancer progression." (PMID 29902261, 2018). "Among the 27 somatic mutations, 24 were restricted to the brain metastases, of which 4 affected cancer-related genes (i.e., FGFR2, MAP2K4, ATR and PIK3CA)." (PMID 29755676, 2018). "Finally, our data supports several studies demonstrating that AKT-signaling may be both dependent and independent of PIK3CA mutations in cancer." (PMID 28860563, 2017).
cancer (continued). "The cytotoxicity effect of ginkgetin was illustrated in three cancer cell lines, A549 (EGFR, PIK3CA, p52 functional), PC9 (EGFR mutant) and NCIH-460 (EGFR, p52 functional, PIK3CA mutant)." (PMID 29190983, 2017). "In 13 human cancer cell line-derived xenografts, tumors with PTEN loss or PIK3CA mutations are sensitive to PX-866, whereas those harboring RAS-activating mutation show resistance, suggesting that RAS mutation may be an important prognostic predictor of PX-866 for cancer treatment." (PMID 28592260, 2017). "Among these, the mRNA levels of PIK3R1 and CTNNB1 were increased more than 2-fold, and those of PIK3R3, PIK3CA and AKT3 were increased 1.6- to 1.9-fold after co-culture with cancer cells." (PMID 28173828, 2017). "Notably, in both cases, PIK3CA mutations did not affect the total AKT level (data not shown), suggesting that different PIK3CA mutations in different cancer types may selectively activate AKT via signaling transduction, rather than expression regulation." (PMID 27356755, 2016). "Various cancer-related genes were also differentially expressed significantly, including BRAF, BRCA2, VEGFA, VEGFB, RET, PIK3CA, CTNNB1 and GNAS." (PMID 27350898, 2016). "PIK3CA has been named as the key oncogenic effector and could be a potential driver mutation in tumorigenesis of ESCC and these mutants have previously shown oncogenic effects in vivo and may act as a p otential target site of treatment as in other cancer types." (PMID 26528858, 2016). "In a preclinical platform from Cancer Cell Line Encyclopedia, PIK3CA-amplified tumors were sensitive to BYL719, a PI3K α-selective inhibitor." (PMID 27016421, 2016). "PIK3CD, PIK3R2 and PIK3CA are all members of the Class I phosphoinositide 3-kinase (PI3K) enzymes, which have been shown to be involved in several types of cancer and involved in the Akt/mTOR pathway." (PMID 26473850, 2015). "Third, we identified several novel and recurrent kinase fusions that very likely play a role in cancer, such as those involving the MET proto-oncogene and PIK3CA (phosphatidylinositol-4,5-bisphosphate 3-kinase, catalytic subunit alpha)." (PMID 25204415, 2014). "It is worth noting that five of these genes (PIK3CA, HRAS, AKT1, ETV6, and KDM5C) are known to play important roles in cancer and are CGC genes (that is, experimentally validated cancer genes)." (PMID 25360158, 2014). "PIK3CA, which is the catalytic subunit p110 α of PI3-kinase, has been demonstrated to play an oncogenic role in some human cancers in vivo and in vitro." (PMID 24511546, 2014). "Among them, the following well-known cancer genes were found: MET, CDK4, MDM4, EGFR and PIK3CA (amplifications), and CDKN2A, MLLT3, HRAS, CARS and NF1 (deletions)." (PMID 23408991, 2013). "Similar findings for EREG high vs. low were seen when we examined complex cancer genotypes: a) KRAS+BRAF, both wild type vs. any mutant, b) KRAS+BRAF+PIK3CA+NRAS, all wild type vs. any mutant." (PMID 23374602, 2013).